BCOR (BCL6 corepressor)
Diseases named in the same sentence as BCOR in open-access papers (continued):
Sharing a sentence is not in itself a finding about the gene and the disease.
sarcoma (continued). "In contrast to BCOR’s role as a tumor suppressor in leukemia, activating BCOR alterations and translocations are common in pediatric sarcomas and CNS neuroectodermal tumors (CNS HGNET-BCOR), which have transcriptional profiles reminiscent of BCOR overexpression." (PMID 34617019, 2021). "BCOR-CCNB3 sarcoma (BCS) is a group of undifferentiated small round cell sarcomas harboring the BCOR gene rearrangement which shares morphology with the Ewing sarcoma family as well as other malignant round blue cell tumors, thus making them difficult to diagnose." (PMID 34103053, 2021). "BCOR rearranged sarcomas, which may have a round-cell or spindle-cell morphologic appearance, harbor fusion transcripts from BCOR gene fusions with CCNB3, MAML3, or ZC3H7B genes." (PMID 33801953, 2021). "For instance, in two tumors (one endometrial stromal sarcoma and one sarcoma NOS) FISH indicated a rearrangement of the BCOR gene with an unknown partner." (PMID 32351889, 2020). "Recently defined CIC-rearranged sarcomas and sarcomas with BCOR genetic alterations may occur in the retroperitoneum." (PMID 32867125, 2020). "BCOR is another SWI/SNF component gene that might affect high-grade sarcomas in young patients, such as clear cell sarcomas of kidney." (PMID 32972432, 2020). "It is essential to know that even though BCOR immunostain is positively expressed in most BCOR-rearranged sarcomas, it could be negative in rare variants and can be detected in diverse non-BCOR-altered mesenchymal neoplasms." (PMID 40705064, 2025). "However, histopathological evaluation confirmed a diagnosis of BCOR-rearranged sarcoma." (PMID 40932977, 2025). "Nevertheless, Ewing sarcomas, sarcomas with BCOR alteration, and mesenchymal chondrosarcomas frequently originate in bone with a broad site distribution but a preference for the long bones in Ewing sarcomas and sarcomas with BCOR alteration, as is also seen in (S)COS." (PMID 38332052, 2024). "Interestingly, molecular methods could identify subgroups by specific molecular driving events like CIC or BCOR-rearranged sarcoma." (PMID 34780010, 2022). "The other patient presented sarcoma with BCOR-ITD of the undescribed length of duplication, with typical BCOR and SATB2 expression." (PMID 39930783, 2025). "BCOR-CCNB3 sarcoma is a rare, high-grade, undifferentiated small round cell sarcoma with a specific gene fusion between the BCOR (BCL6 corepressor) and CCNB3 (Cyclin B3) genes." (PMID 40932977, 2025). "BCOR alteration sarcoma includes at least three molecular subcategories: BCOR::CCNB3 fusions, BCOR-alternative non-CCNB3 partner fusions and BCOR ITD." (PMID 40948502, 2025). "BCOR is a highly sensitive marker for identifying small round cell sarcomas with BCOR gene alteration, although other reports have suggested that BCOR is less specific than CCNB3 in the diagnosis of BCOR::CCNB3 sarcomas (BCSs) and is often observed in SS." (PMID 39062853, 2024). "Along these lines, different HOX family members were found among the most upregulated genes in a BCOR::MAML3 sarcoma when compared to Ewing sarcoma with EWSR1::FLI1 fusions and CIC::DUX4 positive sarcomas." (PMID 38611033, 2024). "Round cell sarcomas with BCOR alterations usually harbor BCOR::CCNB3 and BCOR::MAML3 genetic fusions, and CIC-rearranged sarcomas are characterized by CIC::DUX4 chimeric transcript." (PMID 39021466, 2024). "In contrast to CIC::DUX4 rearranged round cell sarcomas, BCOR::CCNB3 rearranged sarcomas are more inclined to occur in the bone, whereas CIC rearrangement sarcomas tend to develop in soft tissues and to follow a more aggressive trajectory." (PMID 38170001, 2023). "In the soft tissue, BCOR genetic alterations, including BCOR ITD, are diagnostically defining for a sarcoma that includes undifferentiated round cell sarcoma and primitive myxoid mesenchymal tumor of infancy morphologic types." (PMID 37686670, 2023).
sarcoma (continued). "The “BCOR rearranged sarcoma” group consisted of BCOR::CCNB3 (n = 18), BCOR‐ITD (n = 7), YWHAE::NUTM2B (n = 3), and MAML::BCOR STS (n = 1)." (PMID 37212486, 2023). "BCOR-rearranged sarcomas (BRS) represent a rare type of small round cells sarcoma and are listed separately as “sarcomas with BCOR genetic alteration” in the latest WHO classification." (PMID 34331570, 2022). "Similar findings of positive TrkA IHC have also been described in BCOR and YWHAE rearranged sarcomas." (PMID 36726909, 2022). "BCOR gene aberrations have further been found in a tumor of the sinonasal cavity (a sarcoma) and in pediatric glioma, resulting in CIITA/BCOR and EP300/BCOR fusion, respectively." (PMID 33099834, 2021). "BCOR-rearranged sarcomas comprise sarcomas with BCOR–CCNB3, BCOR–MAML3 and ZC3H7B–BCOR fusions, and sarcomas with BCOR internal duplications." (PMID 33919988, 2021). "These discordant cases included one single BCOR‐rearranged sarcoma (with a BCOR (exon 15)‐CCNB3 (exon 5) fusion gene detected by Archer) and one single CIC‐rearranged sarcoma (with CIC rearrangement detected by FISH)." (PMID 31965673, 2020). "Of note, CIC-DUX4 translocation sarcomas have been reported to show WT1 staining in >90%, while BCOR-translocation sarcomas were reported to show strong staining of BCOR, BCL-2, cyclinD1, and TLE1 staining in most cases (each 80–90%)." (PMID 32204536, 2020). "In the 5th edition, the WHO classification of soft tissue and bone tumors CIC-fused sarcomas, BCOR-rearranged sarcomas, and round cell sarcomas with EWSR1::non-ETS fusion are distinguished." (PMID 40134582, 2025). "The differential diagnosis includes Ewing sarcoma, BCOR-altered sarcoma, sarcoma with EWSR-1::non-ETS fusion, and other round cell tumors." (PMID 40722508, 2025). "The differential diagnosis includes tumors with small round-cell morphology, mainly round cell sarcoma with EWSR1 non-ETS fusion, CIC-rearranged sarcoma, and sarcoma with a BCOR genetic alteration." (PMID 39158802, 2025). "The latest World Health Organization classification of soft tissue and bone tumors recognizes 4 categories within this group: ES, round cell sarcoma with EWSR1-non-ETS fusions, CIC-rearranged sarcoma, and sarcoma with BCOR alterations." (PMID 40948502, 2025). "These are further subdivided into three entities: CIC-rearranged sarcoma, round cell sarcoma with EWSR1::non-ETS fusions, and sarcoma with BCOR genetic alterations." (PMID 40841513, 2025). "Current research indicates that USRCS can be further categorized into Ewing sarcoma, URCS with EWSR1-non-ETS fusions, CIC-rearranged sarcoma, and sarcoma with BCOR genetic alterations." (PMID 40666499, 2025). "The most recent WHO Classification of Soft Tissue and Bone Tumors recognizes four categories within this group: ES, round cell sarcoma with EWSR1-non-ETS fusions, CIC rearranged sarcoma, and sarcoma with BCOR alterations." (PMID 40948512, 2025). "Towards this direction, the 2020 WHO classification of tumors of soft tissue and bone included a few new entities that can be diagnosed exclusively using molecular methods, such as sarcomas with neurotrophic tyrosine receptor kinase (NTRK) fusions and BCL6 corepressor (BCOR) alterations." (PMID 39001377, 2024). "We hypothesize that the combination of BCOR and GLI1 expression in SSs could predict biological behavior and may provide a possible opportunity as a therapeutic target in these high-grade sarcomas." (PMID 39062853, 2024). "Among these, undifferentiated small round cell sarcomas (USRCSs) comprise multiple subcategories, including the recently described CIC-rearranged sarcomas, sarcomas with BCOR alterations, and non-ETS fused sarcomas (such as NFATC2 and PATZ1 sarcomas)." (PMID 38436779, 2024). "For example, not all BCOR-rearranged sarcomas are positive for BCOR on IHC, and a subset of IMTs are negative for ALK on IHC because they harbor alternative ROS1 or RET gene fusions instead of an ALK fusion." (PMID 38137051, 2023).
sarcoma (continued). "It is important to note that no specific clinical trials have been conducted for BCOR-rearranged sarcomas." (PMID 38170001, 2023). "Among them, three distinct sarcoma subtypes with specific clinical, pathological, and molecular features have been individualized in the last WHO classification, including CIC‐rearranged sarcoma (CIC‐RS), BCOR‐rearranged sarcoma, and SRBCS with EWSR1‐non ETS fusion." (PMID 36537582, 2023). "For example, the non-Ewing round cell sarcoma is now known to be at least four distinct tumours based on various gene fusions: desmoplastic small round cell, non-ETS EWSR1, CIC-rearranged, and BCOR altered sarcomas." (PMID 37504306, 2023). "Currently, three categories are acknowledged: round cell sarcomas with EWSR1 gene fusion with non-ETS family members, CIC-rearranged sarcomas, and BCOR-rearranged sarcomas." (PMID 37720343, 2023). "BCOR (BCL6 corepressor)-rearranged sarcomas (BRSs) are a heterogeneous group of sarcomas previously classified as part of the group of “atypical Ewing” or “Ewing-like” sarcomas, without the prototypical ESWR1 gene translocation." (PMID 36765856, 2023). "In addition, the 2020 WHO classification of tumors of soft tissue and bone included some new entities, which can be diagnosed exclusively using molecular methods, such as sarcomas with NTRK fusions and BCOR alterations." (PMID 37998367, 2023). "In the past 15 years, the characterization of Ewing sarcoma has made significant progress, so that currently three main categories are defined: EWSR1-non-ETS fusions, CIC-related sarcoma, and sarcoma with BCOR gene alterations." (PMID 35681674, 2022). "The latest 2020 WHO Classification of Tumors of Soft Tissue and Bone includes four categories for round cell sarcomas: EwS; round cell sarcoma with EWSR1::non-ETS fusions; CIC-rearranged sarcomas; and sarcomas with BCOR gene alterations." (PMID 36115869, 2022). "Of those, 96 cases were assessed as Ewing sarcoma, 3 as EWSR1-non-ETS round cells sarcoma, 1 as sarcoma with BCOR genetic alteration and 5 cases showed no identifiable line of differentiation and were labelled as USTS." (PMID 35295613, 2022). "When CD99 staining is weak or when ES cannot be confirmed by FISH or RT-PCR, the panels above will be able to detect ES with more unusual gene fusions, CIC or BCOR-rearranged sarcomas or round-cell sarcomas with non-ETS fusions." (PMID 33801953, 2021). "According to the 2020 WHO Classification, undifferentiated small round-cell sarcomas include: Ewing sarcoma, round-cell sarcomas with EWSR1-non-ETS fusions, CIC-rearranged sarcomas, and BCOR-rearranged sarcomas." (PMID 34068344, 2021). "The remaining 15 cases of EWSR1 gene rearrangement- negative undifferentiated small round cell sarcomas (included 2 CIC rearrangement sarcomas and 13 undifferentiated small round cell sarcomas) were negative for BCOR gene rearrangement." (PMID 34103053, 2021). "This group of tumors can be subdivided into capicua transcriptional repressor (CIC)-rearranged sarcomas, Bcl6 corepressor (BCOR)-rearranged sarcomas, sarcomas with EWSR1 fusion to non-ETS family members, and unclassified round-cell sarcomas." (PMID 34068344, 2021). "A note to make is that some of the sarcoma alterations such as BCOR or CIC-DUX4 were not described in the early 2000s." (PMID 34698236, 2021). "On the contrary, ES, BCOR rearranged sarcoma, and poorly differentiated synovial sarcomas, are negative for both nuclear ETV4 and WT1 staining." (PMID 32155762, 2020). "Some small round cell sarcomas previously considered atypical subtypes of Ewing sarcoma are genetically and clinically distinct entities and include CIC (Capicua Transcriptional Repressor)-rearranged sarcoma and sarcoma with BCOR (BCL6 corepressor) genetic alterations." (PMID 32225029, 2020).
sarcoma (continued). "Although highly sensitive, BCOR immunostain might not be the perfect surrogate for a BCOR-rearranged sarcoma, as this marker is increasingly reported in diverse sarcomas lacking BCOR alterations, and it can be absent in BCOR-rearranged sarcomas." (PMID 40705064, 2025). "These genetic alterations closely resemble the genomic profile of other sarcomas that respond to CDK4/6 inhibition, suggesting a potential therapeutic strategy involving CDK4/6 inhibitors, either as a single agent or in combination with MDM2 inhibitors, for BCOR-fusion-positive sarcomas." (PMID 40001568, 2025). "Some studies have focused on investigating the characteristics of round cell undifferentiated sarcomas, demonstrating that these tumors can be categorized into Ewing sarcoma, round cell sarcoma with EWSR1-non-ETS fusions, CIC-rearranged sarcoma, and sarcoma with BCOR genetic alterations." (PMID 40666499, 2025). "In the latest WHO classification, undifferentiated small round cell sarcomas of bone and soft tissue are divided into four distinct categories: Ewing sarcoma (ES), round cell sarcomas with EWSR1::non-ETS fusions, sarcomas with BCOR genetic alterations, and CIC-rearranged sarcomas." (PMID 40722508, 2025). "Both sarcomas with BCOR alteration (cases 12 and 13) were negative for BCOR." (PMID 38332052, 2024). "BCOR::CCNB3 sarcomas predominantly arise in bone rather than soft tissue and exhibit a higher occurrence in children and adolescent males, whereas sarcomas with BCOR internal tandem duplication show a wider age range but usually arise in the first year of life." (PMID 38170001, 2023). "Rare BCOR sarcoma was described in a group of small round cell bone tumors lacking the canonical EWSR1 translocation: only 24 BCOR::CCNB3 positive tumors could be identified in an analysis of 594 sarcoma." (PMID 37212486, 2023). "The same holds true for rearrangements with CIC and BCOR, where FISH and RNA-based analyses may be employed as complementary tools (please see section “Round cell sarcoma with non-ETS-fusions, and CIC/BCOR-rearranged sarcoma”)." (PMID 33919988, 2021). "Interestingly, the tested series of PDX models included five samples from so-called ‘Ewing-like’ sarcomas (3 CIC-DUX4-positive sarcomas and 2 BCOR-rearranged sarcomas), which did not exhibit any BCL11B and GLG1 immunoreactivity." (PMID 32164354, 2020). "BCOR positivity by immunohistochemistry is reported as a nonspecific finding shared across multiple sarcoma subtypes, and while initially thought to be a feature more unique to BCOR-rearranged sarcomas, its presence in a variety of tumors makes it a sensitive but nonspecific diagnostic finding." (PMID 38436779, 2024). "Therefore, immunohistochemistry of CCNB3 and BCOR expression may not be sufficient for diagnosis of BCOR-rearranged sarcomas." (PMID 34103053, 2021). "In this study, they included CIC::DUX4, BCOR-altered, EWSR1::ATF1/CREB1, and YWHAE::NUTM2B sarcomas, as well as fusion-negative SRCSs, reflecting the expanding molecular landscape within this spectrum." (PMID 41514642, 2025). "The recent WHO classification identifies four main categories: Ewing’s sarcoma, round cell sarcoma with non-ETS EWSR1 fusions, sarcoma with CIC rearrangements, and sarcoma with BCOR alterations." (PMID 39941818, 2025). "BCOR immunostain is invariably positive in most BCOR-rearranged sarcomas, including the BCOR::CCNB3, BCOR::MAML3, BCOR-ITD sarcomas, and also in certain non-BCOR-rearranged sarcomas, such as YWHAE::NUTM2B sarcomas." (PMID 40705064, 2025). "Subsequent biopsies from an abdominal deposit indicated a high-grade round cell sarcoma with differentials including BCOR-CCNB3 fusion/BCOR-ITD sarcoma, CIC-DUX4 fusion sarcoma, and EWSR-non-ETS fusion sarcoma." (PMID 38544655, 2024). "Our case had similar pathological features, but the absence of BCOR break-apart signals and cyclin D1 staining opposed the diagnosis of ZC3H7B-BCOR sarcoma." (PMID 32290854, 2020).
acute myeloid leukemia (21 papers, 2013 to 2026). Acute myeloid leukemia (AML) is a group of neoplasms arising from precursor cells committed to the myeloid cell-line differentiation. "BCOR, a gene involved in epigenetic regulation, is frequently inactivated in hematologic malignancies such as acute myeloid leukemia and myelodysplastic syndromes, and its mutations are often associated with poor prognosis." (PMID 40900797, 2025). "Somatic mutations in BCOR have been reported in hematological malignancies, including acute myeloid leukemia and myelodysplastic syndromes, and has also been reported at a low prevalence in other cancers, including lung, endometrial, breast and colon cancers." (PMID 35953586, 2022). "BCOR is thought to regulate transcription and is an important potential driver mutation in a number of cancers including acute myeloid leukaemia and CYLD cutaneous syndrome." (PMID 33670346, 2021). "Recurrent mutations in the BCOR gene have been identified in acute myeloid leukaemia and myelodysplastic syndrome among other cancers; however, its function remains poorly understood." (PMID 30902969, 2019). "BCL6 corepressor (BCOR) is recurrently mutated in acute myeloid leukaemia and myelodysplastic syndrome." (PMID 30902969, 2019). "Among human haematological cancers, BCOR mutations have been reported in an array of cancer types including acute myeloid leukaemia and myelodysplastic syndromes, chronic lymphocytic leukaemia and acute lymphoblastic leukaemia." (PMID 28262675, 2017). "Recently, BCOR has been described as mutated in a subset of acute myeloid leukemia patients; about 50% of which present with both BCOR and DNMT3A mutations suggesting a potential cooperation of the two genes, possibly through an epigenetic mechanisms." (PMID 23577124, 2013). "BCOR mutations have been associated with diseases such as acute myeloid leukemia, and decreased expression of BCOR may similarly lead to poor health outcomes resulting from a lack of gene expression regulation." (PMID 26913089, 2016). "Recurrent inactivating somatic BCOR mutations have been identified in various hematological malignancies, acute myeloid leukemia (AML), myelodysplastic syndrome (MDS), chronic myelomonocytic leukemia, medulloblastoma, and retinoblastoma." (PMID 33468080, 2021). "Acute Myeloid Leukemia (AML) remains challenging to treat, especially in cases with mutations in the BCL-6 co-repressor (BCOR), which are associated with poor prognosis and chemo-resistance." (PMID 41549155, 2026). "BCL6 co-repressor (BCOR) gene variants are involved in oculofaciocardiodental (OFCD) syndrome, acute myeloid leukaemia, renal tumours, and photoreceptor degenerative diseases." (PMID 38957147, 2024). "Inactivating somatic mutations in BCOR were detected in patients with acute myeloid leukemia (AML) and other cancers, suggesting that it might function as a TSG." (PMID 34944094, 2021). "Noncanonical PRC1 complex member BCOR is ubiquitously expressed across adult tissues, and mutations within this gene occur in acute myeloid leukemia (AML), myelodysplastic syndrome (MDS), chronic myelomonocytic leukemia (CMML), and aplastic anemia." (PMID 38028538, 2023). "Poor-risk mutation carriers with AA have a 40% higher risk of clonal evolution to MDS or acute myeloid leukemia (AML) compared with patients with PIGA, BCOR, and BCORL1 mutations." (PMID 38646536, 2024). "However, BCOR mutation rates of male patients were lower in other male predominat malignancies (myelodysplastic syndrome (MDS), 3.8% of men vs 6.5% of women; acute myeloid leukemia (AML), 5.5% of men vs 6.9% of women; EBV-positive gastric cancer (EBV-GC), 14.2% of men vs 20% of women)." (PMID 25980440, 2015). "Among the components of PRC1.1, BCOR and BCLRL1, but not PCGF1 are targeted by somatic gene mutations in various hematological malignancies, including myelodysplastic syndrome (MDS), chronic myelomonocytic leukemia (CMML), and acute myeloid leukemia (AML)." (PMID 37266576, 2023).